SDC4 (syndecan 4)
Diseases named in the same sentence as SDC4 in open-access papers (continued):
Sharing a sentence is not in itself a finding about the gene and the disease.
cancer (continued). "Evidence showed that SDC4 regulates cell migration, cell adhesion, and cytoskeleton development in tumorigenesis and progression, so it is regarded as a probable anti-cancer therapeutic target." (PMID 36199068, 2022). "Analysis of receptor expression on representative carcinoma cell lines demonstrates that all express the critical signaling and adhesion receptors of the Sdc4-organized complex at the cell surface." (PMID 35569509, 2022). "We have defined a novel signaling apparatus organized by Sdc4 that suppresses cell cycle arrest in carcinoma cells, thus allowing their continued proliferation." (PMID 35569509, 2022). "SDC4 contributes to the regulation of cell migration in numerous cancer cell types and several extracellular modulators of this process are identified." (PMID 34282767, 2021). "The chemokine receptor CXCR4 and prominin (CD133) expression has been found to affect the metastatic potential of RMA cells, whereas syndecan-4 and stathmin expression can predict the clinical outcome of many cancer types." (PMID 33947373, 2021). "In this review, we highlighted the numerous functions of SDC4, a transmembrane proteoglycan, in cell motility and we summarized the recent knowledge about the role of SDC4 in cancer cell movement." (PMID 34282767, 2021). "Together, the data found suggest that syndecan-4 level is crucial for understanding the changes involving in malignant transformation, and also demonstrate that syndecan-4 emerges as an important target for cancer therapy and diagnosis." (PMID 33810567, 2021). "Up-regulation of SDC4 has been identified in various malignant tumors such as renal cell carcinoma, melanoma and breast carcinoma." (PMID 33990545, 2021). "First, we checked SDC3 and SDC4 gene expression levels on malignant and healthy tissue on several types of cancer on the TCGA database." (PMID 33117401, 2020). "These experiments on ATX mRNA expression provide information on where ATX is produced before it is secreted into the tumor microenvironment where it attaches to adjacent cells including cancer cells by binding to integrins and syndecan-4." (PMID 32824846, 2020). "Secreted ATX binds to integrins and syndecan-4 on the surface of neighboring cells, including cancer cells." (PMID 32824846, 2020). "Our group recently identified HS proteoglycan syndecan-4 (SDC4) as a new molecule that controls ATXβ interaction with the cancer cell surface through a domain located in the SDC4 core protein." (PMID 31906151, 2019). "Coincidentally, some surface molecules were still expressed at lower levels 1 month after repopulation including Syndecan-4, an important regulator of contact inhibition during cancer metastasis." (PMID 30735499, 2019). "At the other end of the linear subnetwork, there are MMP9 and SDC4, established mediators of cancer invasion and apoptosis." (PMID 30978274, 2019). "In conclusion, our results determined that ATX and SDC4 are engaged in a reciprocal collaboration in cancer cell metastasis." (PMID 30237860, 2018). "We demonstrated here, that among all cell surface heparan-sulfate proteoglycans, syndecan-4 (SDC4) was essential for cancer cell interaction with ATXβ but was restrained by heparan-sulfate chains." (PMID 30237860, 2018). "In conclusion our results determined that ATX and SDC4 are engaged in a reciprocal collaboration for cancer cell metastasis providing the rational for the development of novel anti-metastasis therapies." (PMID 30237860, 2018). "We identified HS proteoglycan syndecan-4 (SDC4) as a new molecule that controls ATXβ interaction with cancer cell surface through a domain located in SDC4 core protein." (PMID 30237860, 2018). "Syndecan-4 promotes cell adhesion, in contrast to syndecan-1, which is increased during malignancies and promotes the aggressiveness of cancer cells." (PMID 28079144, 2017). "Although MLF1 and SDC4 were generally highly expressed in multiple types of cancers, their expression levels varied over a large range." (PMID 29340074, 2017).
cancer (continued). "In the map of proteoglycans in cancer, the proteins of Fn, SDC-4, PKCα, Src, FAK, and ERK were connected with cell migration and invasion." (PMID 29033837, 2017). "Mixed results have also been reported for the Ig superfamily protein CD200 and the transmembrane co-receptor syndecan-4 (SDC4), with both pro- and anti-cancer roles suggested in different situations." (PMID 27144453, 2016). "Both PAR2 and PAR1 activation resulted in up-regulated expression of several genes (CD44, FOSL1, TNFRSF12A, RAB3A, COPEB, CORO1C, THBS1, SDC4) known to be important in cancer." (PMID 21072196, 2010). "SDC4 is a cell-adhesion molecule related to the enhanced adhesion of cancer cells to fibronectin, and functions as a receptor in intracellular signaling." (PMID 21655371, 2008). "SDC4 is known to play a role in cell adhesion, proliferation, and migration, which makes it essential for cancer development, invasion, and metastasis in several cancer types." (PMID 40076757, 2025). "Together, the double-inhibitory mechanism involving the molecular interaction of SERPINE2, HTRA1, and SDC4 as suggested here for NC cell migration in the Xenopus embryo might also regulate cancer cell migration in human metastasis." (PMID 38634469, 2024). "Our findings indicate that while not directly functional, SDC4-rs1981429 has a significant effect on cancer-related pathways, increasing BC risk." (PMID 36152082, 2023). "The SDC4 expression in PAAD tissues and paracancerous tissues was detected by the immunohistochemical method, which showed more brownish-yellow pigments in cancer tissues than that in paracancerous tissues, indicating higher SDC4 expression in cancer tissues than that in paracancerous tissues." (PMID 36199068, 2022). "SDC4 was reported to promote cancer cell progression and angiogenesis." (PMID 35898512, 2022). "The highly expressed cytokine CCL5 in CD8 + T Cells, NK Cells, NKT Cells, CD4 + T Memory Cells, Plasma Cells, and Langerhans Cells work together with SDC1 and SDC4 in Cancer Cells to affect the occurrence, development, and mediation of cancer survival of cancer cells." (PMID 36401283, 2022). "Thus, TN-C promotes cancer cell line migration, invasion and proliferation, as well as the activation of NF-κB signaling, and these effects are dependent on syndecan-4." (PMID 35246056, 2022). "Several works have demonstrated that syndecan-4 gene silencing suppresses the cell cycle progression, decreasing the transition from G1 to S phase and decreasing the levels of cyclin D1 and cyclin E in different cancer cell lines." (PMID 33810567, 2021). "NT4 binds SDC4, thereby target cancer cells and inhibit their migration and FGF-induced invasion." (PMID 34282767, 2021). "The data reviewed in this article support that a targeting of syndecan-4, or a modulation of its expression using already available drugs, may be promising strategy for the treatment of different types of cancers." (PMID 33810567, 2021). "Further research into the broader implications of SDC4’s regulation of receptor expression could have profound implications for understanding tissue homeostasis, wound repair, and pathological conditions such as cancer." (PMID 39716457, 2025). "Furthermore, it seems that SDC4 might be a valuable target for cancer diagnosis and treatment, since it is significantly reduced by trastuzumab and panitumumab." (PMID 37006250, 2023). "A uniquely enriched pathway of all five PCGs (FSTL3, KLF6, MLF1, NR4A3, and SDC4) was “Transcriptional misregulation in cancer” (P = 0.048), suggesting that those five PCGs and their regulating lncRNAs may play roles in transcriptional regulation levels in THCA." (PMID 29340074, 2017). "Collagens, MIF, MDK, APP, and laminin were the most highly expressed, and the top ligand-receptor interactions were CAF derived THBS2/THBS3 with cancer cell CD47, and CAF-derived MDK with cancer cell NCL/SDC2/SDC4." (PMID 38525245, 2024).
cancer (continued). "This suggested that SDC4 and NCL played a fundamental role in cancer cellular processes or were involved in regulatory mechanisms that were essential for various cell states." (PMID 38472225, 2024). "Collagens, MIF, MDK, APP, and laminin were detected as the most significant signaling, and the top ligand-receptor interactions THBS2/THBS3 (CAFs)—CD47 (cancer cells), MDK (CAFs)—NCL/SDC2/SDC4 (cancer cells) as potential therapeutic targets." (PMID 36352420, 2022). "SDC4 expression in PAAD tissues was higher than that in corresponding paracancerous tissues, consistent with the high expression of SDC4 in various cancers." (PMID 36199068, 2022). "Disruption of the Sdc4-organized signaling mechanism using a competitor SSTNEGFR peptide leads to a rapid and global arrest of the carcinoma cells throughout the cell cycle." (PMID 35569509, 2022). "CCL5 is another chemokine that we identified as positively associated with the immune response when bound to different receptors (SDC4, SDC1, and CXCR3 for 16, 15, and 13 cancer types, respectively)." (PMID 34430923, 2021). "To further explore this finding in other cancer types, we performed correlations between a macrophage gene signature panel comprised of 92 genes and SDC3 or SDC4 genes based on TCGA database." (PMID 33117401, 2020). "However, several studies have reported that high expression of syndecan-4 is likely involved in carcinogenesis and cancer progression, indicating that overexpression of syndecan-4 may lead endothelial cells to rapidly proliferate and exhibit malignant features." (PMID 33251971, 2020). "MLF1 was moderately expressed (mean FPKM = 233.73), while SDC4 was apparently highly expressed (mean FPKM = 19772.64) in THCA, among various cancers." (PMID 29340074, 2017). "Although specific SDC-4 inhibitor is currently unavailable, several previous studies demonstrated the efficacy of inhibitors of other SDC family members in cancer treatment." (PMID 28703800, 2017). "Among these, we found interactions that may constitute potential targets for CAFs-based therapies, such as THBS2/THBS3 (myCAF2) and CD47 (cancer cells) or between MDK (CAFs) and SDC2/SDC4/NCL (cancer cells)." (PMID 36352420, 2022). "Glypican proteoglycan (GPC1 and GPC6), core membrane-anchored heparan sulfate proteoglycans, were upregulated in ESCC tissues compared with para-carcinoma tissues, whereas syndecan proteoglycans (SDC1, SDC2, and SDC4), transmembrane heparan sulfate proteoglycans, were downregulated." (PMID 35840985, 2022). "Syndecan-4 connects 2 important signaling pathways (proteoglycans in cancer and ECM–receptors interactions) and it has been reported that blocking interactions between syndecan-4 and fibronectin decreases focal adhesions in cells, leading to increased cell proliferation in tumors." (PMID 33693651, 2021). "In addition, macrophages and endothelial cells secreted large numbers of cytokines which interacted with SDC1, SDC4, and ITGB1 in cancer cells." (PMID 34745098, 2021). "Proteoglycans (including syndecan-4 which we observed in our study) are often found on the cell surface or in the ECM and perform multiple functions in cancer and angiogenesis through their ability to interact with both ligands and receptors that regulate neoplastic growth and neovascularization." (PMID 33693651, 2021). "In particular, the crosstalk between Sdc4 and Vcan is an intriguing interaction hypothesis between DPB and MeDPB because their contribution in cancer progression is known, playing a crucial role in mediating the EMT process." (PMID 31623299, 2019). "Just like SDC4, MLF1 also occupied a critical position in the network and had more interactions than the average gene, which are common characteristics of cancer driver genes." (PMID 29340074, 2017).
cancer (continued). "Although several studies have demonstrated important roles of syndecan-4 in cell behavior and its interactions with growth factors, extracellular matrix (ECM) molecules and cytoskeletal signaling proteins, less is known about its role and expression in multiple cancer." (PMID 33810567, 2021). "While not specific to syndecan-4 alone, a targeting of the heparan sulfate moiety may expand the range of approaches hampering syndecan-4 function in cancer." (PMID 33810567, 2021). "Complete Kaplan–Meier curves and Cox analyses on all cancer entities would be required to evaluate whether or not combined expression of both ENPP2 and SDC4 could predict overall- or disease-free patients survival." (PMID 30237860, 2018).
infection (16 papers, 2011 to 2025). The state of being infected such as from the introduction of a foreign agent such as serum, vaccine, antigenic substance or organism. "There are four different human syndecans, SDC1, SDC2, SDC3, and SDC4, which are implicated in the infection of many different viruses." (PMID 40569080, 2025). "We also found SDC4 to be a protein associated with the later phase of the infection." (PMID 38565620, 2024). "Remarkably, the expression of SDC4 is known to be up‐regulated during various stress conditions such as ischemia, hypoxia, and infection, indicating its adaptive response to environmental challenges." (PMID 39725655, 2024). "We found that when SDC4 was overexpressed in normal rat chondrocytes by infection of Lv-Sdc4, the expression of COL2A1 and ACAN were decreased significantly, the expression of MMP3 was increased, both in mRNA and protein levels." (PMID 36414669, 2022). "A significant increase in aggrecan neoepitope generation was detected by Elisa assay in the culture supernatant of normal rat chondrocytes by infection of Lv-Sdc4 compared with Lv-con335." (PMID 36414669, 2022). "Insights on how DUBs can be turned on during infection came from a study showing that CYLD activity is positively regulated by Syndecan-4 (SDC4), a proteoglycan whose expression is induced by type-I IFN." (PMID 32117959, 2020). "HCV also interacts with heparan sulfates on Syndecan 1 and Syndecan 4 which can facilitate attachment and infection in cell lines." (PMID 32292405, 2020). "Especially, Syndecan 1 and Syndecan 4 have shown to be important attachment receptors for HCV on the surface of hepatocytes thereby facilitating infection." (PMID 32292405, 2020). "Immunostaining of eye sections showed a markedly reduced expression of Sdc1, most prominently at the site of infection, whereas the signal for Sdc4 was unaffected, confirming the biochemical shedding data." (PMID 33293379, 2020). "Silencing of either SDC1 or SDC4 prior to HCV challenge showed that while knockdown of SDC1 modestly but significantly diminished infection, SDC4 knockdown markedly inhibited infection." (PMID 24751902, 2014). "Studies on the expression of syndecan-4 in infection are few." (PMID 29368632, 2018). "The effect of syndecan modulation of target cells had a clear impact on HCVcc infection, with knockdown of SDC1 only modestly affecting the capacity for infection, whereas knockdown of SDC4 resulted in more than 65% decrease in infection, as quantified by qRT-PCR." (PMID 24751902, 2014). "Syndecan-4 is a carrier of heparan sulfate, on which MuHV-4 infection strongly depends, so MuHV-4 may down-regulate syndecan-4 on infected B cells to prevent super-infection." (PMID 22102809, 2011). "For instance, both the CXCL2 chemokine and the mycobacteria receptor syndecan 4 SDC4 were significantly upregulated after PCLS infection with AF2122, Mb3601, or H37Rv in Blonde d'Aquitaine, but not in Charolaise." (PMID 34307535, 2021). "Syndecan 4-mediated transmission of HCV was independent of infection as the B cell-line expressing Syndecan 4 was not infected with HCV (data not shown)." (PMID 32292405, 2020). "Interestingly, langerin also prevented HCV transmission by Syndecan 4-positive cell-lines as well as Mutz-LCs and this transmission is independent of infection." (PMID 32292405, 2020).
adenocarcinoma (4 papers, 2013 to 2021). A common cancer characterized by the presence of malignant glandular cells. "Concerning SCD4, high Toll-like receptor 7 expression is associated with the overexpression of SDC4 in patients with adenocarcinoma, which suggests that its expression is related to metastasis." (PMID 32503508, 2020). "Positive immunostaining was detected for SDC4 in adenocarcinomas, where strong immunostaining was observed throughout the cytoplasm of neoplastic epithelial cells of patients with Gleason 3 and Gleason 4–5 tumors." (PMID 34445387, 2021).
cardiovascular disease (4 papers, 2021 to 2024). "The favourable outcomes associated with high syndecan-4 levels in our study contrasts with other studies showing more incident MI, and poorer outcomes in high-risk individuals and other cardiovascular diseases in patients with high serum levels." (PMID 38739599, 2024). "Although SDC4 is known to play an essential role in cardiovascular disease, the zebrafish Sdc4 function in heart regeneration is unclear." (PMID 38700644, 2024). "Importantly, much of the research conducted to date investigating the effects of syndecan-4 ablation in cardiovascular disease has been performed in male mice." (PMID 36092718, 2022).
heart disease (4 papers, 2011 to 2023). "It is noteworthy that, in the present study, we used the same assay employed in a previous study for measuring syndecan-4, that reported association between syndecan-4 levels and cardiac disease severity." (PMID 29232393, 2017). "HPSE induces SDC4 shedding, as we observed in the conditioned medium of our PDEs, however the pathological significance of SDC4 shedding is in cardiac disease." (PMID 32760722, 2020). "The present work investigates (i) whether circulating levels of syndecan-4 reflect the cardiac inflammatory status in patients with heart disease, and (ii) the effects of immunomodulatory inhibitors used in clinical practice on syndecan-4 levels and shedding in vitro." (PMID 37189684, 2023). "Although its circulating levels were increased post-MI, syndecan-4 did not reflect cardiac inflammatory status in patients with heart disease." (PMID 37189684, 2023). "Our study failed to conclude whether circulating syndecan-4 levels are at all increased in heart disease patients vs. healthy controls." (PMID 37189684, 2023).
metabolic disease (2 papers, 2021 to 2025). A congenital disorder (due to inherited enzyme abnormality) or acquired (due to failure of a metabolically important organ) disorder resulting from an abnormal metabolic process. "Sdc4 modulates cellular functions such as cell adhesion, migration, proliferation, and differentiation and is implicated in metabolic diseases." (PMID 40180176, 2025). "Elevated Sdc4 shedding has emerged as a risk factor for metabolic disorders." (PMID 40180176, 2025). "Increased shed Sdc4 levels in serum are positively correlated with metabolic disorders and NAFLD, while reduced serum Sdc4 level was found in individuals with loss of body weight and fat-free mass after bariatric surgery." (PMID 40180176, 2025). "In summary, the results obtained from the current study concurs with previous reports that show a dysregulation in the expression level of osteoactivin, OPG, SPARC and Syndecan-4 in circulation with metabolic disease state." (PMID 34777249, 2021). "All these studies indicate a potential function of Sdc4 in the pathogenesis of metabolic disorders." (PMID 40180176, 2025).
myopathy (2 papers, 2024 to 2026). A disease of the muscle in which the muscle fibers do not function properly. "Taken together, this work contributes with valuable knowledge on the molecular mechanisms underlying WB myopathy and the role of SDC4 in this chicken myopathy." (PMID 39764382, 2024). "Our research revealed significant molecular and cellular alterations associated with WB myopathy and indicated a role of SDC4 in its pathogenesis." (PMID 39764382, 2024). "Investigation of the potential role of SDC4 in the pathogenesis of WB myopathy revealed a decreased tendency in SDC4 gene expression and increased shedding of its ectodomain." (PMID 39764382, 2024).